NEAT1 (nuclear paraspeckle assembly transcript 1)
Diseases named in the same sentence as NEAT1 in open-access papers (continued):
Sharing a sentence is not in itself a finding about the gene and the disease.
prostate carcinoma (continued). "In summary, this study provides important insights into a unique mechanism of ERα regulation in prostate cancer and identifies NEAT1 as a novel prognostic marker and potential therapeutic target in this disease." (PMID 25415230, 2014). "Further, our results confirmed an oncogenic role for NEAT1 in an experimental animal model of prostate cancer and in cell culture models." (PMID 25415230, 2014). "RNA-fluorescent ISH analysis of benign and advanced prostate tumours, including CRPC and NEPC tumour tissue samples, illustrated significantly upregulated NEAT1 levels in advanced prostate cancer, with enhanced focal staining throughout the tumour tissue." (PMID 25415230, 2014). "We demonstrate that NEAT1 is recruited to the chromatin of well-characterized prostate cancer genes and contributes to an epigenetic ‘on’ state." (PMID 25415230, 2014). "Additionally, a good discriminative ability for serum NEAT1 was reported between non-small cell lung cancer and control groups with AUC = 0.7348 and between prostatic cancer and controls with AUC = 0.729849." (PMID 40730640, 2025). "Evidence suggests that NEAT1 point mutations are drivers for breast and prostate cancers, regardless of little change in NEAT1 transcription levels." (PMID 36139550, 2022). "In prostate cancer, NEAT1 can bind with cyclinL1/CDK19 to promote cancer metastasis." (PMID 36011001, 2022). "Additionally, lncRNA NEAT1 is highly expressed in docetaxel-resistant prostate cancer patients and cell lines." (PMID 34803512, 2021). "Studies found that high m6A level of NEAT1–1 was correlated with bone metastasis of prostate cancer as well as m6A level of NEAT1–1 may be new target for diagnosis and therapy of bone metastatic prostate cancer." (PMID 34899855, 2021). "NEAT1 promotes HMGA2 expression in prostate cancer by acting as a sponge for miR-98-5p." (PMID 31868202, 2020). "Notably, the lncRNA NEAT1 promotes docetaxel resistance in prostate cancer by regulating ACSL4 via sponging miR-34a-5p and miR-204-5p." (PMID 32889799, 2020). "Knockdown of NEAT1 can decrease the malignant behavior of tumor cells for breast cancer, hepatocellular carcinoma, laryngeal squamous cell carcinoma, lung cancer, glioma, prostate cancer, and skin cancer." (PMID 33308223, 2020). "We checked NEAT1–1’s location in P-18 cells, the data showed that transfected NEAT1–1 was located in nucleus in P-18 cell, suggesting the NEAT1–1 may take nuclear function in prostate cancer cell." (PMID 33308223, 2020). "NEAT1 promoted the cell growth of prostate cancer through SRC3/IGF1R/Akt pathway." (PMID 32268876, 2020). "Convincing evidence also showed that NEAT1 drove oncogenic growth in prostate cancer." (PMID 28938549, 2017). "To test this hypothesis in vitro, we evaluated the effect of anti-oestrogens and anti-androgens on NEAT1 levels in prostate cancer cell lines." (PMID 25415230, 2014). "To evaluate this further and to determine whether a functional synergy between ERα and NEAT1 pathways exists in prostate cancer cells, we performed RNA-seq of vector control and NEAT1-overexpressing VCaP cells to determine a NEAT1 signature." (PMID 25415230, 2014). "Interestingly, both ERα and NEAT1 signalling were refractory to AR inhibitors and the lack of AR or ERβ, thus indicating a functional specialization of the ERα-NEAT1 axis for prostate cancer progression." (PMID 25415230, 2014). "Given its significance within the ERα signalling pathway, we propose that targeting NEAT1 might represent a novel and important therapeutic strategy for the treatment of prostate cancer." (PMID 25415230, 2014). "Combinatorial targeting of NEAT1 and AR may represent a unique therapeutic regimen within a subset of patients with advanced prostate cancer." (PMID 25415230, 2014). "Interestingly, knockout of NEAT1 compromised the expression of ERα target genes, suggesting that NEAT1 is not only a downstream target but also a mediator of ERα signalling in prostate cancer cells." (PMID 25415230, 2014).
prostate carcinoma (continued). "Furthermore, the NEAT1 signature was also upregulated in all prostate cancer data sets (comparing benign versus PCa; odds ratio >2.0 and P<1 × 10−6)." (PMID 25415230, 2014). "For example, NEAT1 can regulate the epigenetics of target gene promoters to play the role of oncogenes, by increasing ACSL4 via sponging miR-34a-5p and miR-204-5p, or HMGA2 via sponging miR-98-5p, and was found significantly associated with prostate cancer prognosis." (PMID 35075375, 2022). "Hence, NEAT1 promotes the progression of prostate cancer and may be a therapeutic biomarker in clinical studies." (PMID 36011001, 2022). "Our identification of an ERα-NEAT1 axis illustrates a mechanism whereby prostate cancer cells may develop therapeutic resistance through positive selection of an alternate nuclear receptor signalling pathway in the absence of AR or during androgen ablation therapy." (PMID 25415230, 2014). "Furthermore, introduction of cells overexpressing NEAT1 could clearly induce prostate cancer progression in experimental animal models." (PMID 25415230, 2014). "HyPR-MS has been instrumental in locating prostate cancer-related complexes, including MALAT1, NEAT1, and NORAD." (PMID 40861865, 2025). "For example, NEAT1 can interact with CDC5L and recruit it to the promoter region of AGRN, facilitating prostate cancer’s progression." (PMID 36011001, 2022). "The CCK-8 experiment confirmed that after knocking out NEAT1, the IC50 value of docetaxel on prostate cancer cells decreased significantly." (PMID 34803512, 2021). "In summary, NEAT1 can enhance the expression of ACSL4 by sponging miR-34a-5p and miR-204-5p, thereby promoting docetaxel resistance in prostate cancer cells and accelerating the progression of prostate cancer." (PMID 34803512, 2021). "For example, high expression of the lncRNA nuclear paraspeckle assembly transcript 1 (NEAT1) has been connected with reduced expression of miR-34a and miR-204-5p in CRPC patient tumor samples, prostate cancer cells, and DTX-resistant prostate cancer cells." (PMID 33182737, 2020). "NEAT1 also affects ACSL4 expression by competitively sponging both miR-34a-5p and miR-204-5p in prostate cancer." (PMID 33123488, 2020). "However, the roles of NEAT1 in prostate cancer (PCa) remain largely unknown." (PMID 31481527, 2019). "We assessed the prognostic potential of NEAT1 expression using several statistical measures and correlating it with biochemical recurrence (BCR) and metastasis (MET), prostate cancer-specific mortality (PCSM) and GS>7." (PMID 25415230, 2014). "NEAT1 has been shown to rank among the ERα-regulated long noncoding RNAs that are most highly overexpressed in prostate cancer., according to an integrated study of ERα occupancy and signature in prostate cancer." (PMID 39512820, 2024). "NEAT1 serves as a bridge to facilitate the binding between the major regulatory transcriptional kinase cyclin-dependent kinase 9 (CDK9) and its regulatory subunit cyclin L1 in prostate cancer cells." (PMID 35457249, 2022).
ovarian carcinoma (84 papers, 2016 to 2025). A malignant neoplasm originating from the surface ovarian epithelium. "Our results provided the theoretical foundation for clinical research aiming at combining PARP inhibitors associated with NEAT1 inhibitors to treat ovarian cancer patients." (PMID 38356722, 2024). "In individuals with ovarian cancer, high NEAT1 expression is associated with a worse prognosis and a lower survival rate." (PMID 39337410, 2024). "NEAT1 knockdown causes apoptosis and prevents the colony formation, migration, glycolysis, and proliferation of ovarian cancer cells." (PMID 39337410, 2024). "The current study aimed to investigate the role of the NEAT1/let-7 g axis in the growth, migration, and invasion of ovarian cancer cells and explore underlying mechanisms." (PMID 34416900, 2021). "NEAT1 is significantly upregulated in ovarian cancer, associates with cisplatin resistance and FIGO stage." (PMID 34512721, 2021). "Nucleus enriched abundant transcript 1 (NEAT1), a novel cancer-related lncRNA, is associated with many malignancies, including ovarian cancer, and esophageal squamous cell carcinoma." (PMID 32850952, 2020). "In addition, “PI3K-Akt signaling pathway” and “MAPK signaling pathway” were most closely associated with high NEAT1 expression in ovarian cancer." (PMID 38356722, 2024). "This suggests that the increased levels of NEAT1 found in ovarian cancer could, at least partly, be caused by the elevated levels of the RBP HuR and its stability-promoting effect." (PMID 32340118, 2020). "The expressions of NEAT1 were also found to be up-regulated in prostate cancer, ovarian cancer, and breast cancer and might serve as diagnostic and prognostic biomarkers of cancer." (PMID 29654165, 2018). "Similarly, in the paclitaxel (PTX) resistance of ovarian cancer cells, the NEAT1 level was positively associated with the PTX resistance." (PMID 29654165, 2018). "Moreover, NEAT1 was found to be associated with malignant progression in ovarian cancer and was reported to have clinical significance." (PMID 30154460, 2018). "Therefore, NEAT1 expression in tumor tissues might be associated with the advanced development of ovarian cancer, and these results further strengthen that NEAT1 represents an important biomarker in the prediction of ovarian cancer progression." (PMID 37986114, 2023). "In ovarian cancer xenograft models, NEAT1 knockdown suppresses paclitaxel and cisplatin resistance, thereby reducing tumor growth, supporting the potential of NEAT1 silencing as a chemosensitization strategy." (PMID 41191214, 2025). "Several lncRNAs like ZFAS1, MALAT1, H19 have been shown to increase resistance to cisplatin while lncRNA like GAS5, NEAT1 lower cisplatin resistance in ovarian cancer cells." (PMID 39912983, 2025). "In ovarian cancer, NEAT1 knockdown releases miR-770-5p from sponging, which decreases PARP expression." (PMID 41195272, 2025). "The upregulation of miR-770-5p, by its action as an anti-oncogene, promotes cisplatin sensitivity in ovarian cancers through downregulating the expression of NEAT1." (PMID 40176914, 2025). "NEAT1 has also been related to paclitaxel resistance in ovarian cancer, where it sponges miR-194, leading to ZEB1 overexpression." (PMID 41195272, 2025). "miR-214-3p down-regulation within ovarian cancer impedes cancer cell metastasis by targeting Nuclear Paraspeckle Assembly Transcript 1 (NEAT1)." (PMID 40191724, 2025). "In ovarian cancer cells, a high expression of NEAT1 can increase basic leucine zipper and W2 domain-containing protein (BZW1) and inhibit miR-4500." (PMID 39337410, 2024). "The prognostic value of NEAT1 in ovarian cancer patients was also evaluated in the Kaplan-Meier Plotter database, finding that increased expression of NEAT1 was related to poor prognosis (shorter PFS) of ovarian cancer patients." (PMID 38356722, 2024). "When bound and stabilized by HuR, NEAT1 facilitates the proliferation and invasion of ovarian cancer cells." (PMID 39715205, 2024).
ovarian carcinoma (continued). "NEAT1 knockdown induced synthetic lethality with PARP inhibitors in human ovarian cancer cell lines (HeyA8 and SKOV3)." (PMID 38356722, 2024). "Unexpectedly, using data from the TCGA and GTEx, we found that NEAT1 expression was downregulated in ovarian cancer tissues compared to normal tissues." (PMID 38356722, 2024). "By blocking caspase-3 action, NEAT1 overexpression can also promote cell division and decrease apoptosis in ovarian cancer cells." (PMID 39337410, 2024). "A high level of NEAT1 was correlated with poor PFS of patients with ovarian cancer (P = 0.0369, HR = 1.59) and poor OS (P = 0.073, HR = 1.71), respectively." (PMID 38356722, 2024). "In ovarian cancer, Extracellular vesicles from the TAMs support the immune escape of cancer cells via the transfer of non-coding RNA NEAT1." (PMID 40176927, 2024). "NEAT1 promotes ovarian cancer cells’ EMT, invasion, and migration by mediating the expression of tight junction protein three (TJP3) and blocking the activity of miR-1321." (PMID 39337410, 2024). "A high expression of NEAT1 is strongly connected with distant metastases, tumor stage, and a poor prognosis in ovarian cancer when considered as an independent factor." (PMID 39337410, 2024). "We analyzed the expression level of NEAT1 in nine ovarian cancer cell lines using the online database CCLE." (PMID 38356722, 2024). "The knockdown of NEAT1 increases PTX-induced apoptosis in a cohort of PTX-resistant ovarian cancer cells in vitro, accelerating cell drug sensitivity." (PMID 39337410, 2024). "We analyzed the ovarian cancer cohort from the Cancer Genome Atlas32 (TCGA), for which expression data were available for the polyadenylated NEAT1 transcript." (PMID 38356722, 2024). "Consistent with our results in human ovarian cancer, NEAT1 and miR-214 were also reported to have a reciprocal repression correlation in expressions in human thyroid carcinoma." (PMID 37986114, 2023). "It has been observed that NEAT1 overexpression induced cell proliferation and reduced apoptosis in ovarian cancer cells by suppressing caspase-3 activity." (PMID 37310654, 2023). "NEAT1 expression in human ovarian cancer tissues and cell lines including SKOV-3 and A2780 was investigated through in situ hybridization." (PMID 37986114, 2023). "Taken together, these results demonstrated that NEAT1 increased the expression of angiogenesis-related molecules in human ovarian cancer cells." (PMID 37986114, 2023). "Collectively, these consistent results with indirect or direct evidence again consolidate the oncogenic roles of NEAT1 in promoting angiogenesis in human ovarian cancer cells." (PMID 37986114, 2023). "Our study suggested that NEAT1/miR-214-3p pathway is a potential therapeutic strategy to treat the ovarian cancer." (PMID 37986114, 2023). "Previously, miR-1321 was reported to be involved in ovarian cancer cell invasion and migration, and the downregulation of miR-1321 was reported in ovarian cancer via the upregulation of NEAT1." (PMID 37240034, 2023). "Collectively, these results suggest that NEAT1 expression in human ovarian cancer cells reduced apoptosis and promoted their malignant traits of migration and invasion." (PMID 37986114, 2023). "We aimed to explore the role and mechanisms of the long non-coding RNA NEAT1 (nuclear enriched abundant transcript 1) in regulating angiogenesis and metastasis of human ovarian cancer." (PMID 37986114, 2023). "Collectively, our findings strengthen the role of NEAT1 as a biomarker for ovarian cancer prognosis and progression, with therapeutic implications." (PMID 37986114, 2023). "NEAT1 and miR-214-3p are promising targets for developing therapeutics to treat human ovarian cancer." (PMID 37986114, 2023). "TJP3 is reported to participate in drug tolerance in long non-coding RNA NEAT1-mediaed tumor invasion in ovarian cancer, and it is involved in treatment sensitivity of FPDHP in human cancer cells." (PMID 37950731, 2023).
ovarian carcinoma (continued). "NEAT1 was reported to decrease miR-194 in paclitaxel (PTX)-resistant ovarian cancer tissues and cell lines." (PMID 37310654, 2023). "To explore the potential roles of the lncRNA NEAT1 in the pathogenesis of ovarian cancers, we first evaluated its expression level in cancer samples from patients through in situ RNA hybridization." (PMID 37986114, 2023). "The lncRNA NEAT1 was found to be significantly overexpressed in ovarian cancer cells compared to normal human ovarian epithelial cells." (PMID 37007117, 2023). "In ovarian cancer, high expression of NEAT1 as an independent factor was positively correlated with tumor grade, distant metastasis, and poor prognosis." (PMID 37310654, 2023). "In ovarian cancer patients and cell lines, overexpression of NEAT1 induced the FIGO stage and lymph node metastasis." (PMID 37310654, 2023). "NEAT1 displayed a significantly higher expression level in ovarian cancer tissues, in comparison to that of the paired normal tissues." (PMID 37986114, 2023). "The tumor-promoting roles of NEAT1 in regulating proliferation, migration, and invasion of human ovarian cancer cells have been documented in multiple studies." (PMID 37986114, 2023). "Here, we found that the lncRNA NEAT1 is significantly up-regulated in the ovarian cancer cell lines and clinical cancer tissues in comparison to the corresponding non-tumor cells and tissues." (PMID 37986114, 2023). "NEAT1 has been discovered to be a tumor promoter in ovarian cancer by sponging miR-194 to regulate ZEB1 expression." (PMID 34991683, 2022). "A study showed that NEAT1 can promote the proliferation and invasion of ovarian cancer cells via the upregulation of HMGA2." (PMID 36011001, 2022). "The down-regulation of NEAT1 has been noted to suppress cell proliferation and facilitate apoptosis of ovarian cancer cells." (PMID 34416900, 2021). "NEAT1 expression was elevated while let-7 g was decreased in ovarian cancer clinical tissue samples and cell lines." (PMID 34416900, 2021). "It has been found that lncRNA NEAT1 promotes paclitaxel resistance via competitively binding miR-194 to facilitate ZEB1 expression in ovarian cancer cells." (PMID 34512721, 2021). "NEAT1 is upregulated in ovarian cancer and its knockdown promotes paclitaxel sensitivity of ovarian cancer." (PMID 33820555, 2021). "The lncRNA NEAT1 regulates the proliferation and apoptosis of ovarian cancer cells, providing a potential therapeutic approach for ovarian cancer." (PMID 34461858, 2021). "NEAT1 is overexpressed in cisplatin-resistant ovarian cancer cells and sponges miR-770-5P to upregulate the expression of poly adenosine diphosphate-ribose polymerase 1 (PARP1), which leads to chemotherapeutic resistance in cancer." (PMID 34660304, 2021). "Another study has also reported the implication of NEAT1 in the tumorigenesis and development of ovarian cancer." (PMID 34416900, 2021). "Mouse xenograft models of ovarian cancer cells were established to verify the function of NEAT1 in vivo." (PMID 34416900, 2021). "In a previously conducted study, NEAT1 was confirmed to accelerate the metastasis of ovarian cancer cells." (PMID 34416900, 2021). "The current study established that the expression of NEAT1 was up-regulated whereas that of let-7 g was decreased in ovarian cancer tissues and cells." (PMID 34416900, 2021). "Long non-coding RNAs NEAT1 (nuclear paraspeckle assembly transcript 1) was reported to be correlated with clinically poor paclitaxel response ovarian cancer." (PMID 34512721, 2021). "Consistent with the present findings, another study has previously reported significantly elevated NEAT1 expression in ovarian cancer tissues and cells." (PMID 34416900, 2021). "For example, lncRNA NEAT1 is upregulated in paclitaxel-resistant ovarian cancer cells, which sponges miR-194 to restore the high expression of ZEB1." (PMID 34660304, 2021).